ENSG00000252727
Synonyms: LOC124900334
Gene: Small Cajal body-specific RNA gene on chromosome 12 (8,597,509 to 8,597,640, forward strand). Ensembl gene ENSG00000252727.
Gene Ontology:
Biological process: RNA processing
Cellular component: Cajal body; nucleolus